PRMT1 (protein arginine methyltransferase 1)
Diseases named in the same sentence as PRMT1 in open-access papers (continued):
Sharing a sentence is not in itself a finding about the gene and the disease.
cancer (continued). "Protein arginine methyltransferases (PRMT1-9) have emerged, through their ability to methylate histones and non-histone substrates, as essential regulators of cancers." (PMID 39201539, 2024). "Among nine members of PRMT family, PRMT5, PRMT1, and CARM1 are most highly expressed in cancer." (PMID 39711357, 2024). "Additionally, previous studies reported that ESCC-associated proteins, including PCNA, SLC7A5, CTTN, RB1, EGFR, TP63, and PRMT1, exhibited increased expression in S-III; among these proteins, SLC7A5 and EGFR were FDA-approved drug targets for cancer treatment." (PMID 38652547, 2024). "Since PRMT1 inhibits the cGAS-STING signaling pathway in tumors, methods to directly or indirectly restore cGAS activity and levels can enhance the anti-tumor immune response of cancer cells." (PMID 40018367, 2024). "Likewise, PRMT1 shares common substrates with PRMT5, thus the dual inhibition of PRMT1 and PRMT5 results in potent anti-tumor activity in different cancer models." (PMID 36167829, 2022). "Some of the lysine and arginine methyltransferases widely studied in anti-cancer therapeutics include G9a, EZH2, DOT1L (disruptor of telomeric silencing 1-like protein) and PRMT1 (protein arginine methyltransferases 1), inhibitors of which are being extensively investigated." (PMID 35438143, 2022). "The involvement of PRMT1 in carcinogenesis is no longer questioned due to its overexpression or aberrant splicing observed in numerous types of cancers." (PMID 34833023, 2021). "This interplay between type I and type II PRMTs has recently been shown to have therapeutic value for cancer treatment and thus, it is not surprising that PRMT1 is synthetic lethal to PRMT5 deletion." (PMID 33691794, 2021). "Notably, the contribution of UCP2 to mitochondrial Ca2+ uptake is limited to conditions of enhanced PRMT1 activity and subsequent methylation of MICU1, as the case in most cancer cells." (PMID 33614647, 2021). "Both PRMT1 and PRMT5 support tumor growth and are, therefore, overexpressed in a number of cancers." (PMID 32872669, 2020). "Among nine members of PRMT family, PRMT5, PRMT1 and CARM1 are most highly expressed in cancer (621 cancer cell lines from cancer cell line encyclopedia database) and such high expression is correlated with worse prognosis of patients in a number of cancer types." (PMID 32743345, 2020). "In addition, the local expression of key pathway enzymes (ARG1, ARG2, DDAH1, DDAH2, NOS2, ODC1, PRMT1, and PRMT5), as potential therapeutic targets, was evaluated in reference to cancer pathology." (PMID 32872669, 2020). "Until recently, small molecule inhibition of PRMT1 has not yet been fully explored in cancer therapy largely due to issues pertaining to specificity, selectivity, potency, and cellular permeability." (PMID 32415090, 2020). "Finally, in non-small lung carcinoma, PRMT1 methylates TWIST1 and induces EMT related aggressive cancer behavior." (PMID 31655611, 2019). "Finally, in advanced carcinomas, we expected frequent TWIST1 cytoplasmic expression and co-expression with PRMT1." (PMID 31655611, 2019). "In case of PRMT1-driven methylation, proper mitochondrial Ca2+ uptake is reestablished by increased activity of uncoupling protein 2 (UCP2), pointing to an importance of these proteins for cancer cell survival and activity." (PMID 29113301, 2017). "Notably, in this particular type of cancer also UCP2 expression was lower than in the adjacent normal tissue, possibly demonstrating that the mRNA expression of UCP2 and PRMT1 is dependent on the respective other protein." (PMID 29113301, 2017). "Our study reveals a major role of PRMT1 and UCP2 in cancer cell viability and proliferation as well as in patients’ overall survival probability, indicating that numerous different cancer types utilize upgraded mitochondrial Ca2+ uptake to meet their greatly enhanced energy demand." (PMID 29113301, 2017).
cancer (continued). "However, an increased PRMT1 activity also results in methylation of MICU1 and a reduced mitochondrial Ca2+ uptake/activity would counteract the elevated demand of cancer cells on Ca2+-triggered ATP production in the mitochondria." (PMID 27642082, 2016). "Overexpression of PRMT1 and PRMT6 has been previously reported in various cancer types." (PMID 22987071, 2012). "Additionally, PRMT1 methylates and activates key transcription factors in critical signaling pathways, such as NF‐κB, STAT3, and HIF‐1α, therefore influencing cancer progression." (PMID 41256732, 2025). "Moreover, indirect inhibition of PRMT1, as well as targeting the PTM of cGAS, can be combined with each other or with immune checkpoint blockade for effective strategy to enhance the anti-tumor immunity of cancer cells." (PMID 40018367, 2024). "Additionally, PRMT1 binds to ATF4 in a BTG1-dependent manner, methylating ATF4 and promoting the transcription of certain target genes of ATF4, leading to increased apoptosis of cancer cells." (PMID 38326807, 2024). "High SRSF1 arginine methylation by PRMT1 promotes the exon inclusion of AURKA and RAD1, leading to the accumulation of the oncogene isoforms of these genes, which are involved in the regulation of cancer cell growth, metastasis, DNA repair, and drug resistance." (PMID 39201539, 2024). "To demonstrate the inhibitory effect of PRMT1 in cancer immune surveillance through methylation of cGAS in vivo, we measured immune cell infiltration in a syngeneic mouse model of engraftment with either CT26-cGAS-WT or CT26-cGAS-KO cells after treatment with PRMT1 inhibitor MS023." (PMID 37193698, 2023). "PRMT1 dimethylated CHTOP, and both enzymes could dimethylate arginine-3 on histone H4, but it is the action of PRMT1 that mainly activated the transcription of several cancer-related genes." (PMID 37887293, 2023). "Among these, the mRNA expression of BUB3, DHX9, PRMT1, THOC4, THOC7, U2AF1, and ZNF207 (BUGZ) were found to increase in several primary tumors compared to healthy tissues, while SRSF1 (ASF/SF2) was downregulated in most cancers (except for acute myeloid leukemia—LAML)." (PMID 36553448, 2022). "Obviously, further studies are required to explore the interrelation between UCP2/3 expression and PRMT1 activity in cancer and to reveal whether or not this function of UCP2/3 is causally linked to altered UCP2/3 expression levels in various cancer cells." (PMID 27642082, 2016). "We thus speculate that PRMT1 may probably function as an intermediate factor linking the two distinct cellular activities, i.e., EMT and cellular senescence, which play apparently distinct roles in tumorigenesis and cancer progression." (PMID 26813495, 2016). "Thus, it is possible that Omomyc may affect the PRMT1/PRMT5/MEP50/CHTOP complex, impairing cancer-related gene expression." (PMID 26563484, 2015). "Furthermore, PRMT1 and PRMT6 have also been shown to regulate cancer cell proliferation." (PMID 25847239, 2015). "FBXO7 expression is diminished in human HCC tissue, and its expression level exhibits a negative correlation with the methylation levels of PRMT1 and PHGDH, presenting novel molecular pathways and possible therapeutic targets for cancer treatment." (PMID 41256732, 2025). "Together, our data support developing inhibitors that are selective for PRMT1 and PRMT3, but not for PRMT4 and PRMT6, to eliminate cancer persistence." (PMID 39699269, 2025). "Herein, we report the development of a bioavailable, peptoid-based PRMT1 inhibitor that induces cell death in MDA468 and HCT116 cancer cell lines while not exhibiting any significant impact on nontumorigenic HepaRG or normal human mammary epithelial cells." (PMID 35764172, 2022). "As an example, our analysis results highlight the significant increase in the methylation level of PRMT1’s promoter in BRCA, LUAD, and LUSC compared to the control groups (P<0.05), regardless of the cancer stage, even though the gene was significantly upregulated in LUSC only." (PMID 37506102, 2023).
cancer (continued). "It is worth mentioning, however, that lack of PRMT1 and PRMT5 elevation in tumors might not necessarily mean that enzyme expression is not affected by cancer." (PMID 34439753, 2021).
tumor (138 papers, 2008 to 2026). "In vivo experiments further demonstrated that PRMT1 enzyme activity mutation potently suppressed subcutaneous tumor growth, concomitantly inhibiting M2 polarization and promoting M1 polarization of intratumoral macrophages." (PMID 40858547, 2025). "A Spearman correlation analysis plot indicates that PRMT1 expression is linked to tumor progression." (PMID 40927753, 2025). "Our initial aim was to clarify the role of PRMT1—a protein arginine methyltransferase previously linked to tumor proliferation—in mediating lung metastasis and chemoresistance, given its uncharacterized function in these contexts." (PMID 40927753, 2025). "The expression of PRMT1-9 is commonly elevated in tumor tissues, and this upregulation is frequently linked to poor prognostic outcomes." (PMID 40791817, 2025). "Here, we revealed a novel association between PRMT1 inhibition of tumor macrophage polarization and cGAS/STING in a GC model." (PMID 40858547, 2025). "We identified PRMT1 in GC cells as a prognostic factor that not only drives tumor-associated macrophages (TAMs) toward tumor-promoting subtypes but also reduces apoptosis in GC cells by suppressing the cGAS-STING pathway." (PMID 40858547, 2025). "A similar trend in circ-PRMT1 expression was observed across subgroups stratified by tumor location, with elevated circ-PRMT1 levels consistently associated with poor prognosis regardless of anatomical site." (PMID 40724932, 2025). "B_C3 exhibited a high expression of PRMT1, which suggests a potential link between tumor-associated signatures of B cells and elevated PRMT1 levels." (PMID 38918785, 2024). "Under the stimulation of high-risk factors associated with alcohol consumption, PRMT1 functions normally to prevent tumor formation." (PMID 38326807, 2024). "PRMT1 overexpression has been associated with tumor progression, making it a significant target for therapeutic intervention." (PMID 38326807, 2024). "In summary, it was well known that the expression levels of PRMT1-6 are frequently elevated in tumor tissues and their overexpression is often associated with a poor prognosis." (PMID 38911125, 2024). "To explore how Prmt1 regulates tumor growth, we determined the global transcriptional changes induced by the loss of Prmt1 expression via RNA-seq." (PMID 37673892, 2023). "We also counted the PRMT1‐positive cells in the OS and benign tumour tissues and calculated the pathological scores associated with PRMT1 expression." (PMID 34155784, 2021). "Protein arginine methyltransferase-1 (PRMT1) is associated with the progression of various tumor types and the process of epithelial to mesenchymal transition (EMT)." (PMID 31655611, 2019). "Statistical analysis of the results, concerning semiquantitative measurements of PRMT1 expression, showed association between the expression of PRMT1-v1 splice variant and clinical and histological data of the tumours." (PMID 19078953, 2008). "Importantly, this tumor‐suppressive function of PRMT1 appears specific to alcohol‐associated carcinogenesis." (PMID 41256732, 2025). "This suggests that PRMT1 deficiency may enhance tumor immunogenicity and trigger an immune-activating response." (PMID 40858547, 2025). "Notably, after PRMT1 knockdown, M1-like tumor-associated macrophage (TAM) infiltration increased, whereas M2-like TAM infiltration decreased in vivo and in vitro." (PMID 40858547, 2025). "In addition, immunofluorescence staining for the cell proliferation marker KI-67, along with hematoxylin and eosin (HE) staining, confirmed that the loss of PRMT1 clearly inhibits tumor growth compared with the control group." (PMID 40675804, 2025). "Notably, elevated PRMT1 levels in HCC are linked to larger tumor size, increased microvascular invasion, elevated tumor, node, metastasis (TNM) stages, and poorer survival outcomes, positioning them as potential prognostic indicators." (PMID 38997696, 2024).
tumor (continued). "In addition, tumor-associated macrophages (TAMs) secrete the IL-6 cytokine, which triggers PRMT1 to mediate the formation of asymmetric dimethylation of the oncogene EZH2 at arginine 342, reinforcing EZH2 stability and leading to BC metastasis." (PMID 39201539, 2024). "By exploring the function and regulatory mechanisms of PRMT1, we sought to deepen our understanding of the mechanisms underlying tumor occurrence, identify new therapeutic targets and strategies, and enhance the efficacy of tumor treatment." (PMID 38326807, 2024). "PRMT1 can reverse the immune evasion of tumor cells caused by necroptosis." (PMID 38326807, 2024). "Consequently, it has been observed that PRMT1 is frequently overexpressed in tumor tissues, and its overexpression is often associated with poor prognosis." (PMID 38326807, 2024). "We next determined the causal effect of PRMT1 in tumor immune surveillance in vitro and in vivo." (PMID 37193698, 2023). "In line with our hypothesis, recent studies have already linked the expression of either UCP2 or PRMT1 to tumor growth, state of metastasis and chemo resistance." (PMID 29113301, 2017). "The persistence-reducing efficacy of PRMT1 reduction across cell lines motivated in vivo studies to investigate the potential of PRMT1 reduction to delay tumor relapse." (PMID 39699269, 2025). "In pancreatic ductal adenocarcinoma (PDAC), PRMT1 supports tumor growth by regulating RNA metabolism, cell cycle genes, and β-catenin signaling." (PMID 41204384, 2025). "These complementary therapeutic strategies—activating WHSC1 to reinforce antigen presentation and inhibiting PRMT1 to lift epigenetic repression—offer a dual-pronged approach to enhance tumor immunogenicity." (PMID 41359051, 2025). "Analyses of clinical samples, cell lines, patient‐derived organoids, and xenograft models reveal that PRMT1 promotes tumor growth and CBP resistance through a novel, methyltransferase‐independent mechanism." (PMID 40270464, 2025). "Using PDO models, which preserve tumor heterogeneity and histological characteristics, we further evaluated the impact of PRMT1 silencing on CBP response." (PMID 40270464, 2025). "Together, our work provides evidence for the role of PRMT1 in tumor immunotherapy and reveals a novel function of PRMT1 in macrophage polarization in GC." (PMID 40858547, 2025). "This cascade ultimately suppresses PDAC tumor growth, establishing PRMT1 oligomerization as both a critical driver of PDAC progression and a promising therapeutic target." (PMID 40675804, 2025). "Targeting PRMT1 enhances tumor sensitivity to T cell-mediated killing and improves responses to anti-PD-1/OX40 therapy, highlighting its potential as a target to overcome ICB resistance." (PMID 41204384, 2025). "In other words, should a PRMT1 inhibitor target the tumor, or can it be administered systematically?" (PMID 40001488, 2025). "The combination of PRMT1 inhibitors with anti‐PD‐1/PD‐L1 immunotherapy can synergistically modify the tumor immune microenvironment and bolster the antitumor immune response." (PMID 41256732, 2025). "Nevertheless, our PDX cohorts consistently showed tumor growth inhibition and increased sensitivity to combination therapy, supporting the clinical relevance of targeting PRMT1 in HNSCC." (PMID 40270464, 2025). "Upon injection of cells with overexpressed PRMT1 into nude mice, tumor growth rate was notably accelerated, culminating in increased tumor volume and weight." (PMID 40927753, 2025). "Only a few studies have suggested that PRMT1 is highly expressed in GC and promotes tumor progression." (PMID 40858547, 2025). "The PRMT1 inhibitor GSK3368715 can increase T cell-mediated anti-tumor immune responses and sensitize immune-resistant tumors to PD-1 inhibition." (PMID 39885614, 2025).
tumor (continued). "In summary, we identify the PBX2‐PRMT1‐SWI/SNF‐IGF2BP2 axis as a key driver of tumor growth and CBP resistance in HNSCC, revealing non‐methyltransferase functions of PRMT1 and its potential as a therapeutic target to enhance CBP efficacy." (PMID 40270464, 2025). "In oncology, aberrant PRMT1 activity drives key malignant phenotypes such as tumor proliferation, metastasis, therapeutic resistance, and immune evasion." (PMID 41256732, 2025). "After coculture with macrophages, tumor cell apoptosis increased, especially after PRMT1 knockdown in GC." (PMID 40858547, 2025). "MS023, another PRMT1 inhibitor, acts synergistically with anti-PD-1 immunotherapy to enhance anti-tumor responses in TNBC mouse model." (PMID 39885614, 2025). "The microenvironment of the tumor can become more immunosuppressive when the expression of PRMT1 is elevated." (PMID 40001488, 2025). "Both models showed that the combination with doxycycline-induced PRMT1 knockdown significantly reduced the tumor burden from the regression to progression stages." (PMID 39699269, 2025). "The loss of PRMT1 oligomerization results in decreased global ADMA levels and suppresses PDAC tumor growth." (PMID 40675804, 2025). "PRMT1 promotes eIF4F complex assembly and global translation by methylating eIF4G1, thereby driving tumor initiation and progression." (PMID 41204384, 2025). "PRMT1 has been previously shown to be essential for the viability of specific PDAC patient-derived xenograft tumor models." (PMID 41168397, 2025). "Consistent with CDX findings, PRMT1 knockdown significantly inhibited tumor growth, and tumors in the PRMT1 siRNA group showed heightened CBP sensitivity." (PMID 40270464, 2025). "Inhibiting PRMT1 activity effectively restricts tumor cell growth, positioning it as an attractive target for therapeutic intervention." (PMID 40675804, 2025). "PRMT1 functions as a principal regulator of arginine methylation, critically driving malignant tumor progression via diverse molecular mechanisms." (PMID 41256732, 2025). "Preclinical studies indicate that PRMT1 inhibitors, when used in conjunction with platinum‐based drugs, exhibit a synergistic effect in inhibiting tumor growth or the HIF1α/P300 interaction inhibitor menadione." (PMID 41256732, 2025). "In 2020, the PRMT1-specific inhibitor TC-E-5003 was revealed to be an appealing anti-tumor drug preclinically, especially in combination with the chemotherapeutic drug-loaded injectable NBCA ethyl oleate implant." (PMID 40001488, 2025). "PRMT1 is a key facilitator of tumor angiogenesis, primarily through its regulation of critical proangiogenic factors." (PMID 41256732, 2025). "Immunofluorescence staining of tumor tissues indicated that the expression levels of the different oligomeric forms of PRMT1 were comparable with endogenous PRMT1 in the control group." (PMID 40675804, 2025). "FBXO7 inhibits serine synthesis and tumor growth via ubiquitinating protein arginine N-methyltransferase 1 (PRMT1) in HCC." (PMID 41035649, 2025). "This post‐translational cascade promotes vimentin filament assembly, cytoskeletal remodeling, and tumor metastasis, with PRMT1 inhibition (MS023) reducing metastatic colonization." (PMID 40884268, 2025). "Substantial tumor growth inhibition was observed over 21 d in mice with tumors derived from PRMT1-depleted PANC-1 cells compared to control groups." (PMID 40675804, 2025). "Multivariate Cox analysis showed a significant link between PRMT1 and tumor-node-metastasis (TNM) staging in TNBC." (PMID 40927753, 2025). "Our data so far suggest that HNF4G can cobind with FOXA1 to the same genomic regions, but only HNF4G is essential for tumor growth, in part, by recruitment of PRMT1." (PMID 41168397, 2025).